TSPO2 (translocator protein 2)
Description:
Cholesterol-binding protein involved in the redistribution of cholesterol from lipid droplets to the endoplasmic reticulum. Required to meet cholesterol demands during erythropoietic differentiation. May play a role in transport processes at the plasma membrane of erythrocytes, including regulating VDAC-mediated ATP export, and import of the heme precursors protoporphyrin IX and 5-aminolevulinic acid.
Synonyms: BZRPL1; dJ34B21.2
Tractability: Antibody: UniProt places it where antibodies can reach, with high confidence; its Gene Ontology location is reachable by antibodies, with high confidence; UniProt predicts a signal peptide or a membrane-spanning region; the Human Protein Atlas places it where antibodies can reach.
Gene: Protein-coding gene on chromosome 6 (41,042,467 to 41,044,337, forward strand). Ensembl gene ENSG00000112212.
Subcellular location: Endoplasmic reticulum membrane; Cell membrane
Subcellular location (Human Protein Atlas): Plasma membrane
Gene Ontology:
Molecular function: 5-aminolevulinic acid transmembrane transporter activity; protein binding; cholesterol binding
Biological process: 5-aminolevulinic acid import across plasma membrane; import across plasma membrane; enucleate erythrocyte differentiation; intracellular cholesterol transport; lipid droplet organization
Cellular component: endoplasmic reticulum membrane; organelle membrane; plasma membrane; endoplasmic reticulum; mitochondrial outer membrane; membrane
Genetic constraint (gnomAD): Loss-of-function variants: 20 observed, 17.6 expected, observed/expected ratio (o/e) 1.14, 90% interval 0.8 to 1.64. The upper end of that interval is the gene's LOEUF score, 1.64, which puts it in group 6 of 6, group 1 being the genes least tolerant of losing a copy. Missense variants: 202 observed, 206.38 expected, observed/expected ratio (o/e) 0.98, 90% interval 0.87 to 1.1. Synonymous variants: 81 observed, 95.56 expected, observed/expected ratio (o/e) 0.85, 90% interval 0.71 to 1.02.
Homologues: Orthologues: chimpanzee TSPO2 (100% identical), macaque TSPO2 (96% identical), guinea pig TSPO2 (73% identical), pig TSPO2 (72% identical), rabbit TSPO2 (72% identical), dog TSPO2 (71% identical), rat Tspo2 (67% identical), mouse Tspo2 (65% identical), zebrafish tspo (38% identical), Drosophila melanogaster Tspo (32% identical), Caenorhabditis elegans tspo-1 (22% identical). Paralogues in human: TSPO (37% identical).
Diseases named in the same sentence as TSPO2 in open-access papers:
TSPO2 is named in the same sentence as 3 diseases in open-access papers, as found by Europe PMC text mining. Sharing a sentence is not in itself a finding about the gene and the disease. The quoted sentences say what the papers report.
anemia (1 paper, 2020). A reduction in the number of red blood cells, the amount of hemoglobin, and/or the volume of packed red blood cells. "The major difference was that the failure of definitive erythropoiesis in RhoA deficiency caused profound reduction in maturing erythroblasts and fetal death, whereas TSPO2 deficiency caused modest and compensated anemia." (PMID 32358067, 2020).
Hypocholesterolemia (1 paper, 2020). An decreased concentration of cholesterol in the blood. "Because hypocholesterolemia due to increased cholesterol requirements has been demonstrated in patients with chronic anemia, we measured the plasma cholesterol levels in Tspo2-deficient mice." (PMID 32358067, 2020).
tumor (1 paper, 2014). "Other candidate markers of this set of patient's serum are apoptosis regulator like MTEFD1 and TSPO2 as well as a transcription factor, CRX whose expression and function is essential for growth of tumor cells with photoreceptor differentiation." (PMID 25437182, 2014).